AFAP1 (actin filament associated protein 1)
Description:
Can cross-link actin filaments into both network and bundle structures (By similarity). May modulate changes in actin filament integrity and induce lamellipodia formation. May function as an adapter molecule that links other proteins, such as SRC and PKC to the actin cytoskeleton. Seems to play a role in the development and progression of prostate adenocarcinoma by regulating cell-matrix adhesions and migration in the cancer cells.
Synonyms: AFAP-110; AFAP; AFAP110
Tractability: PROTAC: ubiquitination databases record sites on it; its protein half-life has been measured.
Gene: Protein-coding gene on chromosome 4 (7,758,713 to 7,939,926, reverse strand). Ensembl gene ENSG00000196526.
Subcellular location: Cytoplasm, cytoskeleton, stress fiber
Subcellular location (Human Protein Atlas): Actin filaments; Cytosol; Focal adhesion sites
Gene Ontology:
Molecular function: molecular adaptor activity
Biological process: regulation of signal transduction
Cellular component: actin cytoskeleton; focal adhesion; actin filament; cytosol; plasma membrane; stress fiber
Genetic constraint (gnomAD): Loss-of-function variants: 68 observed, 90.65 expected, observed/expected ratio (o/e) 0.75, 90% interval 0.62 to 0.92. The upper end of that interval is the gene's LOEUF score, 0.92, which puts it in group 3 of 6, group 1 being the genes least tolerant of losing a copy. Missense variants: 1,185 observed, 1,064.6 expected, observed/expected ratio (o/e) 1.11, 90% interval 1.06 to 1.17. Synonymous variants: 506 observed, 437.8 expected, observed/expected ratio (o/e) 1.16, 90% interval 1.07 to 1.24.
Homologues: Orthologues: chimpanzee AFAP1 (99% identical), macaque AFAP1 (99% identical), dog AFAP1 (91% identical), rat Afap1 (90% identical), pig AFAP1 (89% identical), mouse Afap1 (82% identical), guinea pig AFAP1 (80% identical), tropical clawed frog afap1 (79% identical), zebrafish afap1 (69% identical), rabbit AFAP1 (58% identical). Paralogues in human: AFAP1L1 (43% identical), AFAP1L2 (36% identical).
Diseases named in the same sentence as AFAP1 in open-access papers:
AFAP1 is named in the same sentence as 28 diseases in open-access papers, as found by Europe PMC text mining. Sharing a sentence is not in itself a finding about the gene and the disease. The quoted sentences say what the papers report.
glaucoma (7 papers, 2017 to 2024). Increased pressure in the eyeball due to obstruction of the outflow of aqueous humor. "Afap1 is enriched in peripheral ON-parasol RGCs, and a variant within AFAP1 has been associated with primary open-angle glaucoma in human patients." (PMID 38994994, 2024). "To date, the response to latanoprost of patients with glaucoma and ocular hypertension, is reported to be associated with the genetic polymorphism of seven genes (ABCB1, SLCO2A1, AFAP1, GMDS, PTGS1, MRP4, and PTGFR)." (PMID 36313286, 2022). "Although the association of AFAP1 and ABCA1 genes with cancer has been widely studied, there is a paucity of data showing the underlying mechanism in glaucoma." (PMID 35741817, 2022). "Genes with type-specific RGC expression patterns included the glaucoma-associated genes SIX6, which was enriched in midget ganglion cells; CAV2 and POU6F2 enriched in ON parasol RGCs and AFAP1, enriched in peripheral ON parasol RGCs." (PMID 32555229, 2020). "Together, existing evidence implies AFAP1’s potential involvement in the pathogenesis of glaucoma." (PMID 37239387, 2023). "Three genetic loci (AFAP1, BICC1, and ABCA1) were identified in four or more approaches in our pipeline, confirming earlier evidence that these genes have a likely role in glaucoma pathogenesis." (PMID 35741817, 2022).
prostate carcinoma (6 papers, 2015 to 2023). A carcinoma that arises from epithelial cells of the prostate gland. "The loss of AFAP1 in prostate cancer cells reduced cell proliferation and tumorigenesis in nude mice." (PMID 25925763, 2015). "AFAP1 is upregulated in certain cancers and AFAP1 expression is associated with higher grades of prostate cancer." (PMID 26340021, 2015). "Increased AFAP1 abundance is an unfavorable prognostic marker in lung and renal cancers and promotes tumorigenesis of prostate cancer." (PMID 37094077, 2023). "The function of the AFAP1 gene in oncogenesis has been investigated in both breast and prostate cancer." (PMID 25925763, 2015). "The function of AFAP1 has been studied mainly in prostate cancer and breast cancer where AFAP1 contributes to the progression of cancer by regulating the adhesion of cancer cells." (PMID 26340021, 2015).
breast carcinoma (3 papers, 2015 to 2021). "It has been reported that AFAP1 regulates Src activity and promotes the formation of actin stress fibers and focal adhesions in breast cancer cells." (PMID 25925763, 2015).
esophageal adenocarcinoma (2 papers, 2013 to 2022). A malignant tumor with glandular differentiation arising predominantly from Barrett mucosa in the lower third of the esophagus. "In esophageal adenocarcinoma, high-resolution methylome analyses have shown hypomethylated noncoding DNA regions and upregulated lncRNA in actin filament-associated protein 1 (AFAP1) antisense RNA 1 (AFAP1-AS1)." (PMID 23843741, 2013).
liver cancer (2 papers, 2021 to 2023). An epithelial or non-epithelial malignant neoplasm that arises from the liver. "Of interest, we found that circ-ZEB1 and circ-AFAP1 are strongly correlated with liver cancer stemness and a poor prognosis, and can regulate the epithelial-mesenchymal transition (EMT) process." (PMID 38053070, 2023).
melanoma (2 papers, 2004 to 2020). A malignant, usually aggressive tumor composed of atypical, neoplastic melanocytes. "Among them we identify BIRC3, SLIT2, GBP2, and AFAP1 to be involved in the acquisition of BRAFi resistance in melanoma cell lines." (PMID 32708687, 2020).
open-angle glaucoma (2 papers, 2024). Chronic outflow obstruction of the eye's drainage canals that can lead to increased internal eye pressure and optic nerve damage. "We found a novel NRS consisting of a VNTR with a repeat unit of 24 bp located in the second intron of AFAP1 that was associated with small intestine cancer and open-angle glaucoma." (PMID 38364871, 2024).
ovarian carcinoma (1 paper, 2016). A malignant neoplasm originating from the surface ovarian epithelium. "APAF1 partially abrogated paclitaxel resistance, suggesting that besides downregulation of AFAP1, other mechanisms are involved in mediating the effect of miR21 on paclitaxel resistance in ovarian cancer cells." (PMID 27021436, 2016).
pancreatic cancer (1 paper, 2021). "All these genes are upregulated in pancreatic cancer, and seven of them are significantly associated with unfavorable prognosis (MET, YAP1, PTPN14, EPS8, AHNAK, RALB, and AFAP1)." (PMID 34957301, 2021).
cancer (9 papers, 2014 to 2026). A tumor composed of atypical neoplastic, often pleomorphic cells that invade other tissues. "In the antisense of the AFAP1 gene, the AFAP1-AS1 gene has been known as an oncogenic long non-coding RNA in human carcinoma." (PMID 38929750, 2024). "In four female carcinoma samples (COAD, HNSC, LUSC, and PAAD), three genes (AFAP1, NINJ2, and HOOK2) were commonly identified as classifiers, and the overexpression of the three genes was related to oncogenesis." (PMID 38929750, 2024). "More interestingly, the adaptor proteins in the AFAP family, AFAP1 and AFAP1L1, are also involved in cancer." (PMID 24995146, 2014).
tumor (6 papers, 2014 to 2025). "Our analysis showed AFAP1 was significantly associated with histological type (P = 0.024) and anatomic neoplasm subdivision (P = 0.014)." (PMID 36631800, 2023). "The AFAP1 gene expression levels were increased in the tumor tissues in 36% of the specimens (12/33)." (PMID 24723436, 2014).
AFAP1 also shares sentences with these, for which no sentence is quoted: metabolic syndrome (2 papers); autosomal dominant polycystic kidney disease (1); Barrett esophagus (1); cholangiocarcinoma (1); clear cell renal cell carcinoma (1); cognitive decline (1); exfoliation syndrome (1); Familial adenomatous polyposis (1); gastric cancer (1); Insulin resistance (1); liver diseases (1); Lynch syndrome (1); osteosarcoma (1); polyposis (1); renal carcinoma (1); small intestine cancer (1); thyroid tumor (1).